PCAT1 (prostate cancer associated transcript 1)
Diseases named in the same sentence as PCAT1 in open-access papers (continued):
Sharing a sentence is not in itself a finding about the gene and the disease.
retinoblastoma (1 paper, 2018). A malignant tumor that originates in the nuclear layer of the retina. "The results of microarray analysis showed that lncRNAs HOTAIR, CCAT1, DNM3OS, HIF1A‐AS1, MEG3 and 7SK expressions were up‐regulated, and lncRNAs PCAT1, MIR31HG, BCAR4, RRP1B and H19 were down‐regulated within retinoblastoma tissues." (PMID 30030888, 2018).
thyroid (1 paper, 2025). "Our findings strongly suggest that both PCAT1& FENDRR may potentially play a role in thyroid carcinogenesis and could be a useful biomarkers in differentiating PTC from benign thyroid lesions." (PMID 40468332, 2025).
cancer (88 papers, 2013 to 2025). A tumor composed of atypical neoplastic, often pleomorphic cells that invade other tissues. "Although not much is currently known regarding the specific functions of most of these lncRNAs, MAP3K20-AS1, STARD4-AS1 and PCAT1 are high-risk factors for different cancers and PCAT1 also is known to activate SOX2 as well as affect cGAS/STING signaling." (PMID 40018706, 2025). "The upregulation of lncRNA with oncogenic potential such as HOTAIR, MALAT1, PCAT1, H19 have been reported in various cancer types and have been associated with various processes contributing to cancer development." (PMID 39912983, 2025). "By encouraging PRC2 expression, PCAT-1 overexpression in cancer cells was linked to an increase in in vitro cell proliferation." (PMID 38294554, 2024). "Prostate-cancer-associated ncRNA transcripts 1 (PCAT1) is upregulated in the colon and ovarian cancer, sponging miR-149-5p and miR-124-3p, respectively, which are responsible for cell proliferation." (PMID 37190145, 2023). "In the Tin list, this concerns the genes BDNF Antisense RNA (BDNF-AS), Biotinidase (BTD), Metastasis-Associated Lung Adenocarcinoma Transcript 1 (MALAT1), MicroRNA 210 (MIR210), and Prostate Cancer-Associated Transcript 1 (PCAT1)." (PMID 37736859, 2023). "Several studies have reported that exosomes can mediate lncRNA prostate cancer associated transcript 1 (PCAT1) to participate in a series of biological behaviors of cancer cells." (PMID 36093435, 2022). "Previous studies implicated that PCAT1 was an oncogenic gene and played vital roles in the regulation of cancer development." (PMID 35415876, 2022). "Subsequent researches showed that PCAT1 was deregulated in numerous human cancers and associated with carcinogenesis, clinicopathological features and prognosis." (PMID 35415876, 2022). "Although several studies have revealed that lncRNAs on 8q24, including PRNCR1, CCAT2 and PCAT1, encompass the cancer predisposition SNPs, the prognostic significance of these lncRNAs in GC patients has not yet been fully explored." (PMID 32117633, 2020). "Prostate cancer-associated transcription 1 (PCAT1) undergoes up-regulation in cancer cells to suppress cell death." (PMID 32664703, 2020). "Meanwhile, PCAT1 has been implicated in many types of cancers, and further cancer-associated PCAT1 SNPs have been identified." (PMID 33329688, 2020). "A number of recent studies implicated a role of lncRNA PCAT1 in post-transcriptional regulation of key cancer genes." (PMID 30773595, 2019). "And lncRNA PCAT1 (prostate cancer-associated ncRNA transcript 1)/miR-145-5p/Toll-like receptor 4 (TLR4) signal axis also functions in osteogenic differentiation process." (PMID 31718549, 2019). "Overexpression of PCAT-1 was reported in several cancers and its function is associated with cell proliferation, invasion, metastasis, survival, cell cycle, chemoresistance, and homologous recombination." (PMID 30987615, 2019). "The Prostate Cancer associated lncRNA Transcript 1 (PCAT-1) is a ∼2 kb lncRNA that is polyadenylated, localized to chromosome 8q24 and expressed in neoplastic and metastatic prostate tissues, among other cancers." (PMID 29755696, 2018). "Prostate cancer-associated ncRNA transcript 1 (PCAT-1), although initially reported as a PCAT, has been described to associate with multiple types of cancers." (PMID 28793797, 2018). "Among lncRNAs, we confirm previously-reported downregulation of GAS5 and MEG-3, and identify for the first time dysregulation of cancer-associated H19 and PCAT-1 in HNSCCs." (PMID 27323410, 2016). "Prostate cancer-associated ncRNA transcript 1 (PCAT-1) is a long intergenic non-coding RNA codified by a gene located in a gene desert of chromosome 8q24, about 725 kb from the c-MYC oncogene." (PMID 27148353, 2016). "So far, PCAT-1 expression has been associated to few cancer types such as CRC, and esophageal squamous carcinoma." (PMID 27148353, 2016).
cancer (continued). "For example, transcriptome sequencing in cancer tissues has led to the discovery of novel ncRNAs such as PCAT-1, a specific regulator of cell proliferation and chimeric, cancer-associated RNAs." (PMID 25798919, 2015). "Notably, PCAT1 expression was associated with clinical stage, metastasis and survival of patients with diverse types of cancers." (PMID 39640681, 2024). "PCAT-1 (prostate cancer-associated ncRNA transcript 1) was initially discovered in prostate cancer and may also be related to CRC metastasis." (PMID 38294554, 2024). "PCAT-1 (Prostate Cancer-Associated Transcript 1): Identified in exosomes associated with various cancers, including CRC, PCAT-1 is thought to enhance the secretion of pro-inflammatory cytokines and influence cellular processes such as proliferation, invasion, migration, and apoptosis." (PMID 37760852, 2023). "However, no comprehensive analysis of the association of all tagSNPs of PCAT1 with cancer susceptibility has yet been performed, including for CRC." (PMID 31253700, 2019). "Therefore, it is plausible that targeting PCAT-1 might have potential for Myc associated cancer therapy." (PMID 30987615, 2019). "Thus, the application of PCAT1 rs2632159 and rs1902432 SNPs for cancer risk might be considered from race to race." (PMID 31253700, 2019). "Several SNPs are related to the expression of cancer-associated lncRNAs including CCAT2 and Prostate cancer-associated transcript 1 (PCAT-1) in CRC." (PMID 37025163, 2023). "Prostate cancer associated transcript-1(PCAT-1) is an oncogenic lncRNA, high expression of PCAT-1 is associated with poor overall survival of cancer." (PMID 37805491, 2023). "Another extensively studied lncRNA in cancer is PCAT-1, which has been shown to be upregulated in PCa and to promote cancer cell proliferation, migration, and invasion." (PMID 37686633, 2023). "Given its aberrant expression in diverse cancers and its influence on critical cell functions, PCAT-1 presents as a potential therapeutic target for CRC, particularly for controlling inflammation and modulating tumor–stroma immune interactions." (PMID 37760852, 2023). "This includes the Chromosome 8q24 region, all heavily associated with cancer (over 108 citations), with the MYC locus, as well as with several long non-coding RNAs loci—PCa Associated Transcript 1 (PCAT1) and PCAT2." (PMID 36765779, 2023). "Subsequently, the abnormal expression of PCAT1 was found to be related to the occurrence and development of a variety of malignant tumors, and can lead to chemotherapy resistance." (PMID 35692795, 2022). "Contrastingly, several of the lincRNAs in this region appear to be hotspots for SNPs including PCAT1 and CCDC26 which are associated with 73 and 81 SNPs, respectively, with many of these SNPs associated with various cancers." (PMID 33499210, 2021). "PCAT-1, a lncRNA related to stress resistance, plays a role in drug resistance in a variety of cancers." (PMID 33980216, 2021). "The upregulation of PCAT1, PRNCR1, PVT1, and MYC potentially confers the risk of cancer as their upregulation is strongly associated with prostate cancer." (PMID 32680982, 2020). "For example, oncogenes like PCAT-1, MALAT1, and NDRG4 which associated with progression in pan-cancer had also been identified as prognostic biomarkers in CRC." (PMID 33203797, 2020). "PVT1 and PCAT1, located in the vicinity of the MYC oncogene, are encompassed by the 8q24.21 protein-coding gene desert–a region harboring many cancer risk variants, including CaP risk SNPs in men of African ancestry." (PMID 32059012, 2020). "Abnormal expression of PCAT1, an important regulator of multidrug resistance, is found in many cancers." (PMID 32754285, 2020). "PCAT1 has attracted attention as a potential prognostic marker and therapeutic target in multiple types of human cancer." (PMID 32153626, 2019). "Our results are in agreement with previous studies consistently establishing PCAT1 as a lncRNA promoting cancer progression." (PMID 30773595, 2019).
cancer (continued). "LncRNAs, such as prostate cancer associated transcript (PCAT1 and PCAT3), increase cancer cells proliferation." (PMID 28467474, 2017). "Our results included some well-known cancer-associated lncRNAs such as HOTAIR, PCA3, PCAT1, and CRNDE." (PMID 27147563, 2016). "In addition, PCAT1 regulates expression of multiple miRNAs, which involved in cancer-related pathways including Wnt pathway, Hippo pathway, and NF-κB pathway." (PMID 39640681, 2024). "Therefore, we and others consistently suggest that PCAT1 is a reliable biomarker for cancer diagnosis." (PMID 39640681, 2024). "Additionally, PCAT-1 is involved in non-small cell lung cancer to upregulate cancer cell proliferation, invasion, and migration." (PMID 36699052, 2022). "Similarly, lncRNA prostate cancer-associated transcript 1 (PCAT-1) is also highly expressed in CRC tissues and its cancer cell lines." (PMID 36076273, 2022). "In conclusion, PCAT1 is a positive regulator of cisplatin resistance in cancer cells and targeting PCAT1 may be an effective drug resistance strategy." (PMID 32754285, 2020). "Thus, similar to ANRIL and CCAT2, PCAT1 is a major oncogenic lncRNA and potential prognostic and therapeutic cancer marker." (PMID 33329688, 2020). "The lncRNA, Malat1, controls the expression of genes involved in nuclear processes and synaptogenesis, while the expression of the lncRNA PCAT-1 causes a homologous recombination deficiency and the suppression of the tumor suppressor BRCA2, which has been linked to cancer." (PMID 32922377, 2020). "Besides ANRIL, CCAT2, PCAT1, HULC, and CUPID1/2, there are numerous other cancer-associated lncRNAs listed in the relevant databases, several of which contain disease-associated SNPs." (PMID 33329688, 2020). "Clinical correlation between PCAT1 and cancer progression was also reported in a number of cancers." (PMID 30773595, 2019). "The lncRNA prostate cancer-associated transcript 1 (PCAT-1) showed potential oncogenic roles in different cancers, however its role in HNSCC is not known." (PMID 30987615, 2019). "Other studies conducted in esophageal squamous carcinoma, colorectal cancer and hepatocellular cancer have highlighted the strong potential of PCAT1 as a biomarker of poor prognosis, linking its overexpression to cancer tissue invasion, lymph node metastasis, advanced tumor stage and low survival." (PMID 29755696, 2018). "The discovery of analogous roles for PCAT-1 in two cancer types may indicate its cancer type independent role as a general regulator of the metastatic phenotype, although further confirmation of this is yet to be provided." (PMID 25101115, 2014). "Furthermore, ncRNAs such circRNA_0000140 34, exosomal lncRNA PCAT1 35, lncRNA ODRUL 36, and circular RNA PVT1 37 have the ability to influence the metastasis of cancer and may function as biological markers for diagnostic and prognostic purposes." (PMID 40959103, 2025). "In addition, PCAT1 can also regulate the radiosensitivity of malignant tumors." (PMID 35692795, 2022). "Orilnc1, KIMAT1, SLCO4A1-AS1, LINC01420, KRAS1P, YWHAE, PART1, MALAT1, PCAT-1, lncRNA-NUTF2P3-001 and TP53TG1 are long non-coding RNAs (lncRNAs) whose interactions with KRAS have been verified in the context of cancer." (PMID 35139853, 2022). "Also, in the 8q24 region, lncRNAs prostate cancer-associated transcript 1 (PCAT1) and colon cancer-associated transcript 2 (CCAT2) by affecting DNA break repair and chromosome instability play a role in cancer development, and polymorphisms in these lncRNAs were crucial risks of cancers." (PMID 34337048, 2021). "Our findings highlight the crucial relationship between CAFs and PCAT-1 which establish a CD133/SOX2-related stem cell phenotype and promote cancer cell chemoresistance." (PMID 32754302, 2020). "Our findings highlight the crucial relationship between CAFs and PCAT-1 which triggers a CD133/SOX2-related stem cell phenotype and acquisition of cancer cell chemoresistance." (PMID 32754302, 2020).
cancer (continued). "PCAT1 and PCAT10 were significantly enriched in a CaP-specific manner relative to enrichment in other cancer types." (PMID 32059012, 2020). "Furthermore, PCAT1 could bind to miR-326, a tumour suppressor in diverse human cancers." (PMID 31273188, 2019). "The “MII oocyte lncRNA signature” included the lncRNAs BCAR4, PCAT1, WEE2-AS1 and TUNAR that are involved in cancer, cell cycle and pluripotency." (PMID 29396444, 2018). "This impairment sensitizes cancer cells to PARP1 inhibitors, thus providing PCAT1 the potential to serve as a predictive biomarker of patient responses to PARP inhibitor treatment." (PMID 26690121, 2015). "LincRNAs are gaining increasing importance both as biomarkers in cancer (HOTAIR: breast, liver, pancreas; MALAT-1: NSCLC; PCAT-1: prostate), and as regulators of complex and diverse biological functions." (PMID 24393131, 2014). "The PCAT1 ncRNA is known to repress BRCA2, activate MYC, promote cell proliferation, and is upregulated in prostate, colorectal, and other cancers." (PMID 38981681, 2024). "Multivariate cox regression indicated that the copy number alteration (CAN) of PCAT1 was a prognostic factor independent of age, gender and cancer stage." (PMID 35415876, 2022). "PCAT-1 promotes the expression of PRC2, which induces cell proliferation in cancer cells in vitro." (PMID 36699052, 2022). "Like the recently identified PCAT1, SChLAP1 and PCAT29, the expression of some of the novel EPCATs is functionally relevant and therefore, cancer-associated lncRNAs should not entirely be seen as transcriptional noise due to aberrant regulation." (PMID 25686826, 2015). "It is possible that the risk-related SNPs on 8q24 may control expressions of the encompassed lncRNAs, PCAT1, PRNCR1, and PVT1, in PC cells and further contribute to cancer progression." (PMID 26690121, 2015). "However, there have been no reports between LRAT and OS as well as the lncRNA PCAT1/miR-370-3p/LRAT pathway in cancer." (PMID 40959103, 2025). "The functions of PCAT1, miR-370-3p, and LRAT in OS lung metastasis or cancer chemo-resistance, however, are not well documented." (PMID 40959103, 2025).
tumor (66 papers, 2013 to 2026). "On the other hand, tumor growth promoters like prostate cancer-associated transcript 1 (PCAT1), PVT1, and urothelial cancer associated 1 (UCA1) act as transcriptional repressors, a mir-145-5P sponge, and a P13K/AKT pathway activator." (PMID 37021836, 2023). "PCAT-1-activated CAFs also enhanced the transformation of tumor-associated macrophages (TAMs) into a tumor-supporting M2 phenotype." (PMID 35087824, 2021). "PCAT‐1 knockdown eliminated the tumour‐promoting effect caused by miR‐129 inhibition, probably through repressing MAP3K7 and subsequent NF‐κB activation." (PMID 32048803, 2020). "Furthermore, associations between amplification of PCAT1 and overall survival of patients with tumor were consolidated using analysis of TCGA datasets." (PMID 39640681, 2024). "Down regulation of PCAT-1 can induce T cell recruitment and activate IL-13/IL-33 mediated pathway, inhibit tumor metastasis caused by CAF mediated activation of stromal fibroblasts, enhance the sensitivity of tumor cells to chemotherapy drugs and affect the microenvironment of tumor immune cells." (PMID 39705424, 2024). "Furthermore, the rs710886 SNP in lncRNA PCAT1 is known to lead to the loss of miRNA-145 binding sites, thus resulting in increased levels of PCAT1 expression and the inhibition of tumor cell invasion and proliferation." (PMID 34907261, 2021). "In another study, serum exosomal lncRNA PCAT1 was associated with tumor grade." (PMID 34692482, 2021). "High expression of PCAT1 was associated with advanced clinical-stage and tumor metastasis." (PMID 33842553, 2021). "In fact, overexpression of PCAT‐1 in HNSCC patient samples compared to adjacent non‐tumor tissues was also noted." (PMID 40231344, 2025). "Elevated serum exosomal PCAT1 levels were observed in patients with advanced pathological stages, indicating a possible link between PCAT1 and tumor progression." (PMID 39640681, 2024). "Our results indicate that serum exosomal PCAT1 provides a rapid assessment of therapeutic outcomes, suggesting its secretion by circulating tumor cells or diffusion from the extracellular environment." (PMID 39640681, 2024). "Meanwhile, PCAT-1 knockdown prevented the tumor progression when miR-129 was inhibited, potentially achieved by suppressing Mitogen-activated protein kinase kinase kinase 7 (MAP3K7) expression and activating Nuclear factor-kappa B (NF-κB)." (PMID 37987364, 2023). "Of note, the PCAT1 KD group treated with erastin or DTX treatment showed the slowest tumor growth among all groups." (PMID 35402284, 2022). "Inhibition of PCAT1/SOX2 in collaboration with radiation further inhibited tumour growth, and initiated the cGAS/STING signalling pathway, which enhanced the immune responses of radiotherapy in NSCLC." (PMID 35415876, 2022). "PCAT1 deficiency inhibited NSCLC growth and tumorigenicity in vivo, and SOX2 overexpression dampened IR‐induced adaptive immune responses and promoted tumour growth." (PMID 35415876, 2022). "Compared with the control group, xenograft tumor weights were significantly lower in the PCAT1 KD group." (PMID 35402284, 2022). "Our studies suggested the potential roles of PCAT1/SOX2 as predictors of tumour responses to the combination of radiation and immune checkpoint inhibitors." (PMID 35415876, 2022). "Our study also found that PCAT1 can promote the proliferation and migration of circulating tumor cells." (PMID 36093435, 2022). "In ESCC tissues, elevated PCAT1 expression is related to tumor lymph node metastasis and clinical staging." (PMID 35241975, 2022). "Subcutaneous tumor-bearing nude mice were used to verify the regulatory effect of PCAT-1 on gefitinib resistance in vivo." (PMID 33980216, 2021). "A recent study found that exosomal lncRNA PCAT-1 involved in tumor stroma remodeling in lung cancer." (PMID 35087824, 2021). "PCAT-1 knockdown reduced tumor volume and weight, and reversed acquired gefitinib resistance in vivo." (PMID 33980216, 2021).